MANF (mesencephalic astrocyte derived neurotrophic factor)
Diseases named in the same sentence as MANF in open-access papers (continued):
Sharing a sentence is not in itself a finding about the gene and the disease.
neurodegenerative disease (17 papers, 2018 to 2025). A disorder of the central nervous system characterized by gradual and progressive loss of neural tissue and neurologic function. "As an ER stress-associated protein, MANF has been implicated in chronic stress and multiple neurodegenerative diseases including AD." (PMID 33994992, 2021). "ER stress can be one of the candidate mechanisms, as MANF is known to alleviate ER stress and elevated ER stress is associated with many neurodegenerative diseases and defects in neurite outgrowth." (PMID 33071755, 2020). "The multi-targeted actions of MANF underscore its potential as a candidate molecule in the treatment of neurodegenerative diseases." (PMID 40437610, 2025). "Recent studies have demonstrated that MANF exhibits neuroprotective effects against various neurodegenerative diseases." (PMID 40437610, 2025). "Cerebral dopamine neurotrophic factor (CDNF) and mesencephalic astrocyte-derived neurotrophic factor (MANF) display cytoprotective effects in animal models of neurodegenerative diseases." (PMID 35129674, 2022). "Previous studies have suggested a function for MANF in the maintenance of neurons based on neuroprotective and neurorestorative effects of MANF in different rodent degenerative disease models." (PMID 32005751, 2020). "Mesencephalic astrocyte-derived neurotrophic factor (MANF) shows protective effects on cells in various models of degenerative diseases." (PMID 31586115, 2019). "Mesencephalic astrocyte-derived neurotrophic factor (MANF) is a potent survival-promoting protein with neurorestorative effect for neurodegenerative diseases." (PMID 30234112, 2018). "Therefore, additional studies are required to further investigate physiological effect of selected miRNAs and contribution of MANF/CDNF in this effect in degenerative diseases." (PMID 34575854, 2021). "MANF exerted neuroprotective effects against ethanol-induced neurodegeneration by alleviating ER stress, which may be relevant to other ER stress-related neurodegenerative diseases." (PMID 33994992, 2021). "This study provides evidence that MANF is involved in neuronal differentiation and it may be a potential candidate to facilitate the regeneration of neuronal processes in neurodegenerative diseases." (PMID 33071755, 2020). "MANF protects against Aβ toxicity by attenuating Aβ-induced ER stress, which may be one of the potential targets for the neurodegenerative diseases related to pathological ER stress, including AD." (PMID 30760285, 2019). "Studying the activity of the CKGC peptide would potentially help to reveal new possibilities in discovery and delivery of drugs against neurodegenerative diseases, but also to find out the details about mechanisms of action of MANF/CDNF that are yet poorly understood." (PMID 30234112, 2018). "Altogether, our study identified ER stress as an integral part of SCA17 pathogenesis, and established piperine as a promising MANF-based therapy for treating SCA17, which also has therapeutic implications for other ER stress associated neurodegenerative diseases." (PMID 29378605, 2018). "Thus, one could consider how to increase endogenous levels of CDNF and MANF in humans to promote healthy aging and possibly prevent or delay the development of neurodegenerative diseases." (PMID 37555005, 2023). "Both MANF and CDNF are protective and restorative in rodent models of neurodegenerative diseases." (PMID 31781038, 2019). "Mesencephalic astrocyte-derived neurotrophic factor (MANF) and cerebral dopamine neurotrophic factor (CDNF) form a family of atypical growth factors discovered for their neuroprotective properties in the central nervous system (CNS) in animal models of neurodegenerative diseases." (PMID 31781038, 2019).
tumor (16 papers, 2019 to 2025). "Meanwhile, correlation analysis between MANF level and clinical variables in ICC showed that high expression of MANF was associated with larger tumor diameter (P = 0.026), TNM stage (P = 0.000), and distant metastasis (P = 0.017)." (PMID 39972058, 2025). "Patients with high MANF expression levels had a significantly higher risk of tumor recurrence (P < 0.05)." (PMID 32382531, 2020). "Patients with high MANF expression levels had a worse prognosis and higher risk of tumor recurrence." (PMID 32382531, 2020). "MANF, also known as ARMET (arginine-rich mutated in early stage tumours), is a small arginine-rich protein found in the ER." (PMID 30543055, 2019). "MANF KO mice exhibited smaller liver size, less tumor number and area, lower liver-body weight ratio, and poorer serum levels of ALT, AST, TBIL, and DBIL than KOfl/fl mice under SBT induction, which was opposite to MANF KI mice." (PMID 39972058, 2025). "MANF deficiency triggers ER stress in RCC cells, suppressing tumor cell proliferation and invasion via the IRE1α pathway." (PMID 41142779, 2025). "IP, HERPUD1, GADD34, HMOX1, and MANF mRNA levels were significantly upregulated in tumor samples, indicating robust activation of all three arms of the UPR." (PMID 41120732, 2025). "Either ALKBH5 knockout or MANF ablation had a more noticeable effect on VHL inactivation 786-O, suggested tumor cell ER stress protective effects and mechanisms of MANF was affected by VHL status." (PMID 40603319, 2025). "Examples include MANF, DCBLD2, and PLK2, which have been linked to tumor-suppressive functions in various cancers." (PMID 41154614, 2025). "We found the liver size, tumor number, tumor area, and liver-body weight ratio in MANF KI mice were significantly increased, compared with MANF KIfl/fl mice after SBT treatment." (PMID 39972058, 2025). "We also investigated the oncogenic role of MANF in ICC by using ICC cell lines, nude mice bearing tumor, hepatocyte-specific MANF knockin (KI)/knockout (KO) modeling mice, and administration of recombinant human MANF (rhMANF)." (PMID 39972058, 2025). "Differential expression analysis of the hyperexpanded clones compared to all other clones revealed an elevated expression of tumor promoting factors/oncogenes (HSPA5, PDIA4, MANF, PPIB) and a gene associated with malignant B cell clones (CD63)." (PMID 36153593, 2022). "In the present study we found that MANF is secreted from several tumor cell-lines upon IFN-γ treatment, both human and murine, and that this secretion is mediated through ER calcium depletion." (PMID 33891607, 2021). "To conclude, we found that MANF is secreted from tumor cells upon IFN-γ treatment, however further studies are needed to elucidate the complete signaling cascade involved in IFN-γ-induced MANF secretion and to establish its immunoregulatory role in cancer." (PMID 33891607, 2021). "However, we did find that MANF knockdown dramatically inhibited tumorigenesis and tumor growth in nude mice subcutaneously injected with Hucct1 cells stably knocked down MANF in the ninth week." (PMID 39972058, 2025). "During the progression of HCC, MANF exhibited tumor‐suppressive properties." (PMID 40103332, 2025). "Because MANF is secreted upon cytokine stimulation and can switch macrophages to M2 phenotype, which is pro-tumorigenic, MANF could potentially serve as an immunoregulator in the tumor microenvironment, and as a drug target." (PMID 33891607, 2021). "Thus, MANF is secreted from IFN-γ-stimulated tumor cells, and further studies are required to assess its potential as a drug target for cancer immunotherapy." (PMID 33891607, 2021). "In correspondence with tumor growth, the mRNA and protein levels of MANF, CK19, and Ki67 were reduced in MANF KO mice, compared with KOfl/fl mice under SBT induction." (PMID 39972058, 2025).
tumor (continued). "In mouse renal cell tumor models, the role of ALKBH5 in promoting tumor growth through the activation of tumor cells UPR and its relationship with MANF were investigated." (PMID 40603319, 2025). "The corresponding heat map further proved that HSP90B1 was positively correlated with the six genes (HSPA5, PDIA3, MANF, PDIA4, CALR, and PDIA6) in various tumours." (PMID 36291587, 2022). "They did not observe the effect of MANF knockdown on the tumor growth in nude mice injected with Hucct1 within four weeks." (PMID 39972058, 2025). "Our results suggest that MANF could serve as a novel biomarker for distinguishing ICC and HCC and predicting ICC tumor stage." (PMID 39972058, 2025). "While MANF was shown to be secreted from pancreatic beta cells, its IFN-γ-induced secretion from tumor cells has never been assessed." (PMID 33891607, 2021).
cancer (10 papers, 2008 to 2025). A tumor composed of atypical neoplastic, often pleomorphic cells that invade other tissues. "MANF had a high expression in cancer tissues (Ca) compared with adjacent para-cancer tissues (Pa) in either protein, mRNA, or the levels in serum." (PMID 39972058, 2025). "To confirm the role of MANF expression in the development of cancer, we used LinkFinder or LinkedOmics to analyze the relationship with common oncogenes and tumor suppressor genes." (PMID 32382531, 2020). "The research on MANF and cancers has been silent for quite a long time." (PMID 36185184, 2022). "Our data could enrich the function of exogenous MANF in cancers, and MANF might act as a small molecule for the treatment of CRC." (PMID 36185184, 2022). "We compared transcriptional levels of MANF in cancer with those in normal tissues using ONCOMINE." (PMID 32382531, 2020). "Mesencephalic astrocyte-derived neurotrophic factor (MANF) inhibits migration and invasion in some cancer cells, but its role in pregnancy-related diseases remains unresolved." (PMID 38164189, 2024). "We found that MANF was always highly expressed in HCC and many other cancers, indicating the significance of MANF in tumorigenesis." (PMID 32382531, 2020). "Furthermore, secretory MANF blocked CRC migration and thereby enriched MANF function in cancer." (PMID 36185184, 2022).
metabolic disorders (8 papers, 2017 to 2024). "MANF’s diverse functions position it as a promising candidate for therapeutic interventions in metabolic disorders." (PMID 37751132, 2023). "Recent studies suggest that MANF performs a crucial part in food consumption as well as energy homeostasis and its involvement in the modulation of metabolic disorders." (PMID 36936164, 2023). "Here, we review the function of MANF based on its structure in neurological and metabolic disorders and summarize its potential applications in disease diagnosis and therapies." (PMID 34745419, 2021). "In addition, MANF is protective against age-related metabolic diseases, because it has been established that metabolic stress and age-related damage in a mouse liver were relieved by systematic MANF supplementation." (PMID 32724497, 2020).
neurological diseases (8 papers, 2018 to 2024). "Owing to the ability of MANF to rescue neuronal loss in several nervous system diseases, we are interested at the profile of MANF induction and potential significance in Aβ pathology." (PMID 30760285, 2019). "MANF is actively being pursued as a therapeutic target for treating neurological diseases such as PD." (PMID 39425207, 2024). "CDNF and MANF have been shown to have therapeutic effects in various neurological disease models via administration of recombinant proteins or via the gene therapy approach." (PMID 31044581, 2019). "On the other hand, mesencephalic astrocyte-derived neurotrophic factor (MANF) is one form of the novel neurotrophic factor and has been found to have cytoprotective effects in neurological disorders." (PMID 38216957, 2024). "The neurotrophic role of mesencephalic astrocyte derived neurotrophic factor (MANF) and cerebral dopamine neurotrophic factor (CDNF) has been demonstrated in several models of neurological diseases and crosstalk with BDNF and GDNF." (PMID 36338029, 2022).
kidney diseases (7 papers, 2018 to 2024). "At 12 weeks, the accelerated progression of kidney disease in the mutant mice deficient of MANF in the TALs became much more pronounced." (PMID 37838725, 2023). "In vivo, secretion of MANF was increased by ER stress in chondrodysplasias and ER-stress induced kidney diseases, suggesting that high ER stress increases MANF secretion in pathological conditions." (PMID 30386256, 2018). "The role of MANF in kidney diseases, however, remains elusive." (PMID 39114033, 2024). "However, the function of MANF has not been investigated in kidney disease in vivo." (PMID 37838725, 2023).
heart disease (3 papers, 2024 to 2025). "In this study, we further extended our previous research on MANF and cardiac diseases to focus on myocardial cell‐derived MANF's influence and mechanism on MH." (PMID 40739335, 2025). "Taken together, these discoveries offer valuable insights into the role of MANF in heart disease and provide important information for the development of novel strategies for heart disease treatment in the future." (PMID 39462320, 2024). "MANF has protective effects against heart disease, diabetes and immunomodulation in addition to its function in the nervous system." (PMID 39242993, 2024). "These discoveries offer valuable insights into the role of MANF in heart disease and provide important information for the development of novel strategies for heart disease treatment in the future." (PMID 39242993, 2024).
cardiovascular disease (2 papers, 2021 to 2023). "MANF is also a good assessment factor for the risk of cardiovascular disease in AGHD patients and has excellent therapeutic potential." (PMID 34220710, 2021). "However, it is undeniable that serum circulating MANF levels may be an excellent target for predicting the onset of AGHD and serve as an excellent potential therapeutic factor for cardiovascular disease in AGHD patients." (PMID 34220710, 2021).
brain disorder (1 paper, 2022). A disease affecting the brain or part of the brain. "In addition, studies have shown that MANF could exert protective functions in multiple brain disorders, such as intracerebral hemorrhage and Parkinson’s disease." (PMID 36585419, 2022). "To date, the function of MANF has been studied in many brain disorders, but not in MDD." (PMID 36585419, 2022).
central nervous system diseases (1 paper, 2023). "MANF is a neurotrophic factor reported to exert protective actions in various central nervous system diseases." (PMID 38012707, 2023).
mental illness (1 paper, 2024). "Until now, the function of MANF in causing mental illness has not been thoroughly investigated in many studies." (PMID 38216957, 2024).
myopathies (1 paper, 2022). "Additional studies are needed to further examine the relationship of MANF and RYR1-related myopathies." (PMID 35698232, 2022).
retinopathy (1 paper, 2017). "Thus, we questioned whether MANF is detectable in the vitreous and whether vitreous MANF levels are associated with retinopathy." (PMID 28367115, 2017). "Vitreous MANF may be a promising protein biomarker for the indirect assessment of retinal disorders, which could provide indirect evidence of retinal pathology." (PMID 28367115, 2017). "Vitreous MANF may be a promising protein biomarker for the indirect assessment of retinal disorders, which could also provide indirect evidence of retinal pathology." (PMID 28367115, 2017). "Finally, we measured the concentrations of MANF in the vitreous of patients with different retinopathies." (PMID 28367115, 2017). "Therefore, we hypothesized that MANF may have therapeutic potential for the treatment of retinopathy." (PMID 28367115, 2017).
skeletal dysplasia (1 paper, 2019). Any Mendelian diseases that affects growth and development of the skeleton. "However, it did not alleviate the intracellular retention of mutant matrilin-3, suggesting that it is the intracellular MANF that is of importance in the pathobiology of skeletal dysplasias." (PMID 30543055, 2019).
MANF also shares sentences with these, for which no sentence is quoted: Alzheimer disease (7 papers); systemic lupus erythematosus (4); colorectal cancer (3); injury (3); spinocerebellar ataxia (3); Intellectual disability (2); melanoma (2); myocardial ischemia (2); Parkinson (2); prediabetes (2); abnormal glucose tolerance (1); age-related macular degeneration (1); Alcohol- (1); alopecia (1); atopic dermatitis (1); atrial fibrillation (1); autosomal dominant tubulointerstitial kidney disease (1); breast carcinoma (1); cerebral infarction (1); cerebrovascular diseases (1); cholangiocarcinoma (1); chronic pancreatitis (1); Cirrhosis (1); colon carcinoma (1); connective tissues diseases (1); COVID-19 (1); developmental delay (1); diabetic retinopathy (1); experimental autoimmune encephalomyelitis (1); fibrosis (1).
A further 16 diseases each share a sentence with MANF in 1 paper.